FKBP5 (FKBP prolyl isomerase 5)
Diseases named in the same sentence as FKBP5 in open-access papers (continued):
Sharing a sentence is not in itself a finding about the gene and the disease.
depression (continued). "Given the important role of GR in regulating stress responses and the evidence for GR resistance in depression, variation of the FKBP5 gene likely is a critical modulator of the relationship between ELS and depression." (PMID 24596569, 2014). "Polymorphisms in the glucocorticoid receptor and its regulator FK506 binding protein 5 (FKBP5) as well as in the CRH type I receptor interact with early life stress in predicting depression or in the case of FKBP5, post-traumatic stress disorder." (PMID 24027503, 2013). "After adverse life events, variants for FKBP5, the human gene that encodes FKBP51 (Human Gene Organization [HUGO] nomenclature), influence risk for subsequent PTSD and depression." (PMID 41567824, 2026). "The findings suggest that enhanced autophagy may be related to the pathology of depression and that Fkbp5, an autophagy regulator, mediates stress‐induced weight loss." (PMID 39715728, 2025). "No valid associations were found for rs3800373 in the FKBP5 gene, although suggestive trends related to depression and self-aggression were noted." (PMID 40869374, 2025). "In PBMCs, NR3C1 hypermethylation with reduced expression and FKBP5 hypomethylation with increased expression correlate with depression severity and suicidal ideation, supporting HPA-axis dysregulation as a key pathological feature and highlighting PBMC methylation as a potential biomarker." (PMID 41589304, 2025). "In humans and animal models, there is evidence of Fkbp5 involvement in depression phenotypes." (PMID 41373593, 2025). "For example, individuals carrying specific FKBP5 risk alleles exhibit greater DNA demethylation in response to childhood abuse, leading to dysregulated HPA axis activity and heightened vulnerability to stress-related disorders such as PTSD and depression." (PMID 40243774, 2025). "Additionally, they observed that mice overexpressing Fkbp5 in the hypothalamus demonstrated a depressed phenotype, which further confirms the role of Fkbp5 in depression." (PMID 40309821, 2025). "Thus, the role of FKBP5 has been implicated in several stress-related mental disorders more directly, such as PTSD and major depressive disorder, and more indirectly, such as bipolar disorder and schizophrenia." (PMID 40149476, 2025). "We examined differences in DNA methylation patterns in the NR3C1 and FKBP5 genes in relation to personality vulnerability to depression, resilience, and perinatal depressive symptoms, whilst also considering possible moderating effects of childhood traumatic events." (PMID 39257475, 2024). "The authors conclude that, given its regulating role in the HPA stress response, FKBP5 could serve as a biomarker or as a target for developing therapeutic interventions for stress-related disorders such as depression." (PMID 38786025, 2024). "Notably, the FKBP5 gene is a pivotal regulatory gene for the FKBP5 protein and has been explored for a potential linkage with depression and post-traumatic stress disorder co-occurrence." (PMID 38916735, 2024). "Specifically, we investigated the genetic and epigenetic correlates of key stress-associated genes (NR3C1, NR3C2, FKBP5, GILZ, SLC6A4) with psychological characteristics (depression, anxiety, and stress) often included in DD diagnostic criteria, as well as with brain EEG findings." (PMID 38391714, 2024). "In contrast, FKBP5 gene polymorphisms did not exhibit an association with susceptibility to depression in some studies from Germany, Denmark, China, and studies involving black subjects." (PMID 38609904, 2024). "Notably, single nucleotide polymorphism and epigenetic marks within the FKBP5 and SKA2 genes have repeatedly been associated with stress-related psychiatric diseases including major depressive disorder (MDD) and PTSD as well as suicide risk." (PMID 38528004, 2024). "Further, our findings did not support a consistent association between FKBP5 methylation and personality vulnerability to depression or with perinatal depressive symptoms." (PMID 39257475, 2024).
depression (continued). "Due to its regulating role in the HPA stress response, FKBP5 could serve as a biomarker, or as a target to develop therapy for stress-related disorders such as depression." (PMID 38338761, 2024). "We hypothesised that FKBP5 methylation mediates the link between CM and adult depression by altering FKBP5 expression and thus the HPA axis stress response, and that this relationship is influenced by rs1360780." (PMID 38338761, 2024). "The results of the study showed that SNPs of eNOS, HSP70, FKBP5, miR-146a, ACE2, MAS1, SGK1, IL-4–589, IL-6–174, TNF-α–308, CRP–717, 5-HTTLPR, and BDNF genes are associated with the comorbidity of coronary heart disease and depression." (PMID 38745947, 2024). "Therefore, in this study we investigated the association between anxiety/depression/chronic pain and OHRQoL/feelings of happiness/polymorphisms in the COMT, HTR2A, and FKBP5 genes in Brazilian adolescents." (PMID 36834016, 2023). "This study provides useful information on associations between anxiety/depression/chronic pain and OHRQoL/feelings of happiness/polymorphisms in the COMT, HTR2A, and FKBP5 genes in Brazilian adolescents, which are important, considering the limited research on this topic involving adolescents." (PMID 36834016, 2023). "Besides some other genes, FKBP5 has an effect on the electroconvulsive therapy effect in resistant major depression cases." (PMID 37398599, 2023). "Concerning the high susceptibility to OSA in mental disorders and the role of FKBP5 in glucocorticoid action, it is plausible to hypothesize that genetic variants of FKBP5, which is a PTSD and depression candidate gene, may have an impact on OSA." (PMID 37274192, 2023). "There were no other significant depression/control differences between FKBP5 gex in any other cell-type groups, suggesting the heightened FKBP5 gex observed in schizophrenia and possibly to a lesser extent in depression was specific to the superficial layer excitatory neurons." (PMID 36729133, 2023). "Accordingly, FKBP5-mediated attenuation of GR function might curtail the psychological and behavioural flexibility that is compromised in people with depression and anxiety." (PMID 37525888, 2023). "This study evaluated anxiety, depression and chronic pain in adolescents as well as associations with oral health-related quality of life, feelings of happiness and polymorphisms in the COMT, HTR2A, and FKBP5 genes." (PMID 36834016, 2023). "Patients carrying FKBP5 rs4713916A or rs6926133A had greater depression scores (Z = –2.003, p = 0.0459 and Z = –2.108, p = 0.0353, respectively), suggesting that those SNPs may be risk alleles for the development of severe DD." (PMID 37051166, 2023). "In lupus patients, the FKBP5 gene variant rs7757037 was linked to depression, but no similar finding was achieved in an adolescent Chinese population in which the association between depressive symptoms and parenting styles was measured." (PMID 37398599, 2023). "Possibly some other polymorphisms, such as FKBP5 rs1360780, rs3800373, and TPH2 G-703T, might also serve as predictors of increased depression risk." (PMID 34590201, 2023). "Reduced methylation levels of the FKBP5 gene have been demonstrated to be associated with depression in some but not all studies." (PMID 36451133, 2022). "In this study, a global reduction of FKBP5 methylation in adolescents with persistent DS was observed, which is consistent with previous studies examining human whole-blood DNA methylation of the FKBP5 gene in relation to depression." (PMID 36451133, 2022). "Research on methylation of HPA-axis genes has suggested that altered methylation levels of the FKBP5 gene may have potential as a biomarker of depression, however, results concerning methylation levels of the FKBP5 gene in depressive symptoms are inconsistent." (PMID 36451133, 2022).
depression (continued). "It is suggested that GR/FKBP5 might be a biomarker for MDD, for it is a key factor in the development and increased susceptibility to depression, and jointly mediate HPA axis function and stress response." (PMID 36297314, 2022). "The prefrontal cortical FKBP5 induction may be used as an mTOR-independent antidepressant to prevent depression." (PMID 35222638, 2022). "Given the close molecular chaperone relation between FKBP5 and HSP90, the assumption that the HSP90 gene polymorphisms may affect the susceptibility to CAD comorbid depression/anxiety is reasonable." (PMID 34178482, 2021). "Importantly, FKBP5 polymorphisms have been consistently associated with stress-related psychiatric disorders such as major depression and PTSD, where a demethylation-mediated increase in FKBP5 expression was identified as causal in risk-allele carriers." (PMID 33649453, 2021). "FKBP5 gene–environment interaction (cG × E) studies have shown diverse results, some indicating significant interaction effects between the gene and environmental stressors on depression, while others lack such results." (PMID 34423378, 2021). "In the present study, however, we could not demonstrate significant differences with any comparisons for SNPs and haplotype combinations of the FKBP5 gene in relation to the depression and treatment response phenotypes, even in the homogeneous TRDI group." (PMID 34516490, 2021). "HSP90, a molecular chaperone of FK-506 binding protein 5 (FKBP5), coordinates with FKBP5 to regulate glucocorticoid receptor (GR) activity; both are factors of several affective disorders, including anxiety, depression, and post-traumatic stress disorder (PTSD)." (PMID 34178482, 2021). "However, the evidence demonstrated that the analyzed anxiety- and depression-related DEGs such as Gria1, Mapk1, Mapk9, and Fkbp5 contributed to anxiety or depression symptoms in rodents." (PMID 33898422, 2021). "Given its associations with CAD and depression, we speculated that the FKBP5 gene may be the gene underlying the comorbidity of CAD and depression." (PMID 32547886, 2020). "A recent meta-analysis found an association of FKBP5 rs1360780 with suicidal behavior but not with depressive disorders, whereas two other FKBP5 SNPs were associated with depressive disorders." (PMID 32860562, 2020). "Cattaneo and colleagues reported a 11% reduction in leukocyte FKBP5 RNA expression in patients with major depression (N = 74), who responded to eight weeks of antidepressant treatment (citalopram or nortriptyline), while no change was observed in treatment non-responders." (PMID 30678080, 2019). "To confirm the depressive changes induced by CVS and to understand the molecular mechanisms in the brain of rats, we also evaluated two important genes used as molecular indicators of depression: Fkbp5 (FK506 binding protein 5) and Tph2 (tryptophan hydroxylase 2)." (PMID 30533439, 2018). "Additionally, molecular biomarkers of depression (expression of Fkbp5 and Tph2) were studied in hippocampus." (PMID 30533439, 2018). "In sum, these findings indicate that FKBP5 might be a very promising target for pharmacological manipulation in depression, PTSD, and anxiety disorders." (PMID 28393267, 2017). "Accordingly, major depressive disorder (MDD) has been linked to a dysfunction in the HPA axis by several studies, and a landmark study from 2004 showed the role of FKBP5 in antidepressant response causing the initial boom in the study of FKBP51 in clinical populations." (PMID 29206196, 2017). "Taken together, these findings suggest that modification of FKBP5 signalling may be a promising strategy for the development of future psychopharmacological agents to treat depression as well as stress‐related disorders." (PMID 28374949, 2017).
depression (continued). "Hypermethylation or hypomethylation of key genes for the development of depression in men, such as the AR, BDNF, 5HTT, FKBP5, and NR3C1 constitute independent risk and resilience factors for depression, AUDs, and suicidal behavior and further interact with the prior described genetic predisposition." (PMID 28096796, 2016). "Comparing previous studies and our present study, the main differences were the target subject samples, particularly for FKBP5; the main phenotypes in the previous studies were child and/or adolescent depression or post-traumatic stress disorder and related depression." (PMID 25517604, 2014). "And although in vitro data suggests the possibility of a causal relationship between FKBP5 expression levels and depression, this has never been tested in vivo." (PMID 21935478, 2011). "Reflecting the complex phenomenology of depression, FKBP5 may play a decisive role only in some cases of depression, and other genes involved in the glucocorticoid system are responsible for the disturbances of the HPA-axis during depressive episodes." (PMID 17081296, 2006). "The expression of autophagy‐related genes (Atg5, Atg7, Atg12, Becn1, Mmp9, Fkbp5, and Map1lc3b), which are reported to be upregulated in the brains of MDD patients, were examined in the hippocampus and midbrain of control and depression model mice." (PMID 39715728, 2025). "In the pituitary gland, we observed a significant increase in FKBP5 protein levels after 42 days of lithium treatment compared to the control group, indicating that FKBP5 protein expression in the pituitary gland may be affected by long-term lithium treatment in an animal model of depression." (PMID 40309821, 2025). "The FKBP5 gene is involved in the regulation of the hypothalamic-pituitary-adrenal (HPA) axis, which is a major stress - response system in the body.Polymorphisms rs1360780 and rs3800373 in the FKBP5 gene were associated with suicidal events in adolescents with treatment-resistant depression." (PMID 40406494, 2025). "This study aimed to determine the changes in the expression of Fkbp5 and its validated regulator, miRNA-511-5p, during short- and long-term lithium treatment in four brain regions: the hypothalamus, hippocampus, pituitary, and frontal cortex in a chronic mild stress rat model of depression." (PMID 40309821, 2025). "FKBP5 might confer a shared genetic risk for both CHD and depression." (PMID 38745947, 2024). "Hence, FKBP5 has emerged as a focal point in the field of depression genetics research." (PMID 38609904, 2024). "Studies have investigated the association between anxiety and depression with polymorphisms in candidate genes involved in the neurotransmitter system and the stress response, such as Catechol-O-methyltransferase (COMT), Serotonin receptor 2A (HTR2A) and FK506-binding protein 51 (FKBP5)." (PMID 36834016, 2023). "Based on the previous studies presented above, we speculate that FKBP5 variations increase genetic vulnerability to depression and PTSD, and its potential role in prolonged HPA axis activation may result in a higher hyperarousal state than non-risk allele carriers." (PMID 37274192, 2023). "In a meta-analysis of the relationship among FKBP5 gene variation, ELS and depression/PTSD, it was found that those carrying T allele in the rs1360780 gene, C allele in the rs3800373 gene, or T allele in the rs9470080 gene had a higher risk of depression or PTSD after early trauma." (PMID 35663561, 2022). "Moreover, the study indicates that FKBP5 might confer a shared genetic risk for both CHD and depression." (PMID 32860562, 2020). "As diathesis-stress research highlighted, the interaction of FKBP5 variability with childhood, but not adult trauma, has been found to confer risk for several psychopathological phenotypes, including depression, psychosis, anxiety, suicidal attempts, aggression and post-traumatic stress disorder." (PMID 29466454, 2018).
depression (continued). "Moreover, the FKBP5 genotype has been reported to interact with the MDD diagnosis to predict structural neuroanatomical changes, as well as with prior lifetime trauma and/or stress to increase the risk for depression." (PMID 29206196, 2017). "Similarly, FKBP5 minor alleles seem to amplify the negative effects of CT on depression, threat-related brain activity, psychotic symptoms and cortisol levels later in life." (PMID 24658422, 2014). "Meta-analyses highlight the potential moderating effects of these genes (FKBP5, CRH, CRHR1) on HPA axis regulation and the impact of stressful life events on depression, with FKBP5 being particularly notable." (PMID 39438757, 2025). "In the midbrain, the expression levels of Fkbp5 and Mmp9 were significantly higher in CIS‐depression model mice than in control mice." (PMID 39715728, 2025). "In the hippocampus, the expression levels of Fkbp5, Mmp9, and Map1lc3b were significantly higher in CIS‐depression model mice than in control mice." (PMID 39715728, 2025). "In a study of patients with major depressive disorder of European ancestry, the interaction of FKBP5, SKA2, and NR3C1 genes with CT in SA was analyzed, showing a significant interaction between FKBP5 and CT." (PMID 41300231, 2025). "In the present study, Fkbp5, MMP9, and Map1lc3b mRNA expressions were upregulated in the depression model mice compared with the control mice." (PMID 39715728, 2025). "Third, although Fkbp5 mRNA expression was correlated with stress‐stimulated weight loss in depression model mice, it does not allow us to postulate a direct causal relationship between Fkbp5 and weight loss because decreased appetite and food intake may be confounding factors." (PMID 39715728, 2025). "Studies in depression show decreased H2K9ac at BDNF, in schizophrenia where H3K27me3 is modified at GAD1, in PTSD with repressive marks on FKBP5, and in addiction where changes in H3 acetylation impact reward circuits." (PMID 41234420, 2025). "Expression of FKBP5 is reported to be GRE regulated, and Drd4 is a reported biomarker of depression." (PMID 37819629, 2024). "Here, we performed an extensive, large-scale postmortem study (n = 1024) of FKBP5/1, examining neocortical areas (BA9, BA11 and ventral BA24/BA24a) derived from subjects that lived with schizophrenia, major depression or bipolar disorder." (PMID 36729133, 2023). "Some studies have also reported other genes, such as the mineralocorticoid receptor gene (NR3C2), the promotor of serotonin transporter gene (SLC6A4), and FK506-binding protein 5 (FKBP5) with ELS and depression." (PMID 36517640, 2023). "The FKBP5 gene has emerged as one of the most promising and comprehensively studied candidate genes for PTSD and depression thus far." (PMID 37274192, 2023). "Post hoc analysis revealed that this was driven by + 39.8% higher FKBP5 gex in subjects with schizophrenia (t = 3.226, P = 0.001403, FDR = 0.004209) and depression (+ 23.86%; t = 2.478, P = 0.01377, FDR = 0.020655)." (PMID 36729133, 2023). "UCMS induced anhedonia and hopeless behavior in mice, and changed expression levels of the depression-related genes BDNF, CREB, GR, SGK1, FKBP5, IL-1β, IL-6, and TNF-α in the frontal cortex and hippocampus." (PMID 34358084, 2021). "KBD and imipramine reversed the UCMS-induced increase in FKBP5 mRNA expression in the hippocampus and frontal cortex, which provides evidence for the specific targets of KBD in the treatment of depression." (PMID 34358084, 2021). "The KBD formula normalized UMCS-induced anhedonia and hopeless behaviors in mice by restoring expression of the depression-related genes BDNF, CREB, GR, SGK1, FKBP5, IL-1β, IL-6, and TNF-α in the frontal cortex and hippocampus brain regions." (PMID 34358084, 2021).